FGF14-AS2 (FGF14 antisense RNA 2)
Gene: Long non-coding RNA gene on chromosome 13 (102,394,578 to 102,395,707, forward strand). Ensembl gene ENSG00000272143.
Diseases named in the same sentence as FGF14-AS2 in open-access papers:
FGF14-AS2 is named in the same sentence as 4 diseases in open-access papers, as found by Europe PMC text mining. Sharing a sentence is not in itself a finding about the gene and the disease. The quoted sentences say what the papers report.
breast carcinoma (1 paper, 2020). "To investigate the biological functions of FGF14-AS2 in breast cancer, we performed loss- and gain-of-function studies in MDA-MB-231 cells." (PMID 33083023, 2020).
tumor (2 papers, 2016 to 2023). "FGF14AS2 inhibits tumour progression in many ways, such as inhibiting metastasis by regulating the miR-370-3p/FGF14 axis." (PMID 36844873, 2023). "Furthermore, the expression of FGF14-AS2 has been shown to be negatively correlated with tumor size, lymph node metastases, and clinical stage in two independent cohorts, indicating that it might act as a tumor suppressor gene." (PMID 27608009, 2016).
FGF14-AS2 also shares sentences with these, for which no sentence is quoted: glioma (1 paper); liver cancer (1).